NAB1 (NGFI-A binding protein 1)
Description:
Acts as a transcriptional repressor for zinc finger transcription factors EGR1 and EGR2.
Tractability: Antibody: the Human Protein Atlas places it where antibodies can reach. PROTAC: UniProt records ubiquitination sites on it; ubiquitination databases record sites on it.
Gene: Protein-coding gene on chromosome 2 (190,646,746 to 190,692,769, forward strand). Ensembl gene ENSG00000138386.
Subcellular location: Nucleus
Subcellular location (Human Protein Atlas): Nucleoplasm; Plasma membrane; Golgi apparatus
Pathways (Reactome):
Developmental Biology: EGR2 and SOX10-mediated initiation of Schwann cell myelination
Signal Transduction: NGF-stimulated transcription
Gene Ontology:
Molecular function: transcription coregulator activity
Biological process: negative regulation of DNA-templated transcription; regulation of DNA-templated transcription
Cellular component: nucleoplasm; nucleus
Genetic constraint (gnomAD): Loss-of-function variants: 19 observed, 42.72 expected, observed/expected ratio (o/e) 0.44, 90% interval 0.31 to 0.65. The upper end of that interval is the gene's LOEUF score, 0.65, which puts it in group 2 of 6, group 1 being the genes least tolerant of losing a copy. Missense variants: 444 observed, 551.38 expected, observed/expected ratio (o/e) 0.81, 90% interval 0.74 to 0.87. Synonymous variants: 189 observed, 209.13 expected, observed/expected ratio (o/e) 0.9, 90% interval 0.8 to 1.02.
Homologues: Orthologues: chimpanzee NAB1 (100% identical), rabbit NAB1 (98% identical), pig NAB1 (98% identical), guinea pig NAB1 (95% identical), mouse Nab1 (93% identical), rat Nab1 (92% identical), macaque NAB1 (90% identical), dog NAB1 (87% identical), tropical clawed frog nab1 (67% identical), zebrafish nab1b (64% identical), zebrafish nab1a (55% identical), Drosophila melanogaster nab (32% identical), and 1 more. Paralogues in human: NAB2 (42% identical).
Diseases named in the same sentence as NAB1 in open-access papers:
NAB1 is named in the same sentence as 50 diseases in open-access papers, as found by Europe PMC text mining. Sharing a sentence is not in itself a finding about the gene and the disease. The quoted sentences say what the papers report.
cardiac hypertrophy (5 papers, 2012 to 2025). "Mechanistically, circNAB1 translates into a novel protein, NAB1‐356, which is highly expressed in human cardiac hypertrophy." (PMID 40145839, 2025). "Cardiac hypoplasia is caused by the deletion of tmem87b in zebrafish while mice overexpressing Nab1 are resistant to cardiac hypertrophy." (PMID 33031577, 2020). "Additionally, Nab1, a repressor of EGR, has been shown to be a potent inhibitor of pathological cardiac hypertrophy and EGR1 deficient mice have a blunted catecholamine-induced hypertrophy response and are more sensitive to stress." (PMID 26011708, 2015). "The cardiac hypertrophy marker Nab-1 was measured in db/db hearts." (PMID 22474596, 2012). "Notably, the top negative correlate Nab1 (Ngfi-A-binding protein 1) is a transcriptional repressor described as a negative regulator of pathological cardiac hypertrophy." (PMID 30854227, 2019).
breast carcinoma (4 papers, 2013 to 2025). "In the blue module, two CpGs were identified as hubs from the gene body of NAB1 (NGFI-A Binding Protein 1), a protein coding gene involved in transcription factor binding and implicated in Breast Cancer." (PMID 32493224, 2020). "Meanwhile, compared with normal breast epithelium cells, the expression levels of IKZF2, NAB1, S100B were significantly downregulated in breast cancer cells." (PMID 40520263, 2025). "The top autosomal DNAm sites were mapped to genes that have been associated with breast cancer and other malignancies (e.g., cg02325951 on FOXN3, cg20262915 and cg19765154 on NAB1, and cg07850329 on BAG1), as well as childhood neurodegeneration (e.g., cg12607525 on UBTF)." (PMID 36966332, 2023). "Compared with normal breast epithelium cells, RFX5, VEGFA were upregulated in breast cancer cells, IKZF2, NAB1, S100B were downregulated in breast cancer cells while F2R, S1PR2 showed no significance." (PMID 40520263, 2025).
rheumatoid arthritis (3 papers, 2020 to 2023). A chronic, systemic autoimmune disorder characterized by inflammation in the synovial membranes and articular surfaces. "These NAB1 variants are also in moderate linkage disequilibrium (r2 = 0.66), with a variant previously identified in systemic sclerosis and rheumatoid arthritis, which acts as an expression QTL for NAB1 expression in lymphoblastoid cell lines." (PMID 36580032, 2023).
autoimmune disease (2 papers, 2018 to 2023). A disorder resulting from loss of function or tissue destruction of an organ or multiple organs, arising from humoral or cellular immune responses of the individual to their own tissue constituents. "Almost all variants identified (ZNF365, TNFSF4, NAB1, IKZF4-ERBB3, CTSC, DENND1B, SIRPG, and PRF1) are the same or strongly linked with markers associated with other autoimmune diseases." (PMID 37188663, 2023). "According to the GWAS Catalog and Immunobase, five of these shared loci (PADI4 at 1p36.13, NAB1 at 2q32.3, COBL at 7p12.1, CCL21 at 9p13.3, and GATA3 at 10p14) have been associated with a single autoimmune disease so far and thus they represent new pleiotropic loci in autoimmunity." (PMID 30572963, 2018).
colorectal cancer (2 papers, 2012 to 2025). A primary or metastatic malignant neoplasm that affects the colon or rectum. "We next sought to dissect the mechanisms by which natural variation in 3′-end usage impacted gene expression, using as case studies IRF5 and DIP2B, which lie in genomic regions associated with susceptibility to lupus and colorectal cancer, respectively, as well as NAB1 and EIF2A." (PMID 22916029, 2012).
gastric cancer (2 papers, 2022 to 2025). A primary or metastatic malignant neoplasm involving the stomach. "Ubenimex is a broad-spectrum LPA protein inhibitor which can restrain the LAP proteins in many species, such as Leishmania, human liver fluke, plasmodium and E. multilocularis, and inhibit the migration and invasion in gastric cancer by alleviating the activity of the CD13/NAB1/MAPK pathway." (PMID 36311709, 2022).
atrial fibrillation (1 paper, 2025). A disorder characterized by an electrocardiographic finding of a supraventricular arrhythmia characterized by the replacement of consistent P waves by rapid oscillations or fibrillatory waves that vary in size, shape and timing and are accompanied by an irregular ventricular response. "Intriguingly, NAB1‐356 was absent in atriums with atrial fibrillation (AF), suggesting a disease‐specific expression pattern." (PMID 40145839, 2025).
HCMV infection (1 paper, 2020). "Expression of a NAB1 shRNA in the context of HCMV infection does not significantly affect UL138 expression compared to the parental ΔmiR-US5-2 virus, indicating that miR-US5-2 targeting of GAB1, and not NAB1, mediates the effect of the miRNA on UL138 protein levels." (PMID 32759334, 2020).
Hepatic failure (1 paper, 2023). "On the other hand, liver cirrhosis, fatty liver, and hepatic failure phenotypes were associated with variants in NAB1, CALD1, ZBTB16, GAN, TEMD3, and/or PRDM15 genes." (PMID 37664632, 2023).
Hepatitis C (1 paper, 2011). "The fact that Nab1, a stable interactor and transcriptional co-factor of Erg1 is found in a screen for viral replication of Heptatitis C virus raises the possibility that Nab1/Erg1 is already actively assisting Hepatitis C pathogenesis by helping viral reproduction." (PMID 21423752, 2011).
inclusion body myositis (1 paper, 2023). A slowly progressive degenerative inflammatory disorder of skeletal muscles characterized by late onset weakness of specific muscles and distinctive histopathological features. "We identified more significant associations than those previously reported in IIM for STAT4 and DGKQ in the total cohort, for NAB1 and FAM167A‐BLK loci in PM, and for CCR5 in inclusion body myositis." (PMID 36580032, 2023).
myocardial infarction (1 paper, 2017). Gross necrosis of the myocardium, as a result of interruption of the blood supply to the area, as in coronary thrombosis. "The AKT2/NAB1/SPK1 pathway is a novel regulating factor of macrophage migration and cardiac remodeling after myocardial infarction." (PMID 29383164, 2017).
myocardial ischemia (1 paper, 2025). A disorder of cardiac function caused by insufficient blood flow to the muscle tissue of the heart. "As a master regulator and transcriptional sensor in vascular dysfunction, EGR1 is functionally activated by hypertrophy, myocardial ischemia/reperfusion, and other related cardiac stress, modulated by its corepressor NAB1." (PMID 40145839, 2025).
polymyositis (1 paper, 2023). A rare idiopathic inflammatory myopathy characterized by symmetric proximal muscle weakness and elevated muscle enzymes. "Four non‐HLA regions reached genome‐wide significance, SDK2 and LINC00924 (both novel) and STAT4 in the whole IIM cohort, with evidence of independent variants in STAT4, and NAB1 in the polymyositis (PM) subgroup." (PMID 36580032, 2023).
rheumatic disease (1 paper, 2023). "A recent genome‐wide meta‐analysis of 4 seropositive rheumatic diseases revealed several novel loci, for example, NAB1, DGKQ, and YDJC, where IIM contributed to the association." (PMID 36580032, 2023). "We have identified more significant associations than were previously reported in IIM clinical subgroups, such as NAB1 and FAM167A‐BLK loci in PM and CCR5 in IBM, which also have prior evidence of association with rheumatic disease." (PMID 36580032, 2023).
schizophrenia (1 paper, 2017). A major psychotic disorder characterized by abnormalities in the perception or expression of reality. "These include: VAT‐1, DAD‐1, PAQR9, BCKD, BDH, Prickle4, PP2A, RPL13A, SPRED2, KLP, FAM36A, NAB1, CLSTN3, PEDF‐R, and FZD3 (Frizzled gene previously associated with different psychopathologies, most notably Schizophrenia)." (PMID 27696737, 2017).
cancer (3 papers, 2013 to 2024). A tumor composed of atypical neoplastic, often pleomorphic cells that invade other tissues. "In some malignant tumors, Ubenimex can also inhibit the migration and invasion by alleviating the activity of the LAP (CD13)/NAB1/MAPK pathway." (PMID 38585297, 2024). "The association between CEP192, NAB1 and CRC or other cancers, has not been described in previous studies." (PMID 33920880, 2021).
heart disease (1 paper, 2025). "Since collagens are markers of tissue fibrosis, which is a key factor in AF, we measured collagen‐I levels in heart disease specimens and observed a negative correlation between levels of collagen and circNAB1, but not NAB1 mRNA." (PMID 40145839, 2025).
peripheral neuropathy (1 paper, 2009). A disorder affecting the peripheral nervous system. "In previous studies, mice deleted for Nab2 appeared to have no obvious phenotype, whereas mice lacking both Nab1 and Nab2 developed peripheral neuropathy and abnormalities in skin development, and suffered from early lethality." (PMID 19888474, 2009).
NAB1 also shares sentences with these, for which no sentence is quoted: heart failure (2 papers); lupus (2); systemic sclerosis (2); tumor (2); age (1); allergic disease (1); alopecia areata (1); ankylosing spondylitis (1); asthma (1); atopic eczema (1); Autoimmunity (1); colon cancer (1); Crohn disease (1); Dystonia (1); eczema (1); esophageal cancer (1); fibrosis (1); hepatoma (1); idiopathic inflammatory myopathies (1); infection (1); leukemia (1); liver cirrhosis (1); moderate heart failure (1); primary biliary cholangitis (1); primary sclerosing cholangitis (1); prostate carcinoma (1); psoriasis (1); rectal cancer (1); tauopathy (1); ulcerative colitis (1).
A further 1 disease shares a sentence with NAB1 in 1 paper.